CRP (C-reactive protein)
Diseases named in the same sentence as CRP in open-access papers (continued):
Sharing a sentence is not in itself a finding about the gene and the disease.
diabetes (continued). "The increase in CRP is also closely related to the presence of numerous comorbidities such as diabetes, chronic obstructive pulmonary disease, renal failure and peripheral artery disease, which contributes to the progression of HF, negatively impacting the prognosis of patients." (PMID 36189198, 2022). "Diabetes also has a bidirectional relationship with lean body mass loss through low-grade systemic inflammation, which can be marked by interleukin-6 (IL-6), tumor necrosis factor-alpha (TNF-alpha), C-reactive protein (CRP), and white blood cell count." (PMID 36362539, 2022). "As Hs-CRP is a sensitive inflammatory marker, it helps to detect pre-diabetes." (PMID 36381804, 2022). "Previous studies have found that TACE treatment experience, liver cancer surgery or transplantation history, diabetes, chronic liver disease history, pain history, CRP level, ECOG score, preoperative anxiety, and postoperative TACE are risk factors for severe abdominal pain post-TACE." (PMID 35941895, 2022). "The covariates of age above 60, female sex, c-reactive protein (CRP) > 50 mg/L, O2 saturation <90%, underlying cardiovascular disease, hypertension (HTN) and diabetes mellitus, and beta-blockers were used as inputs in the multivariable regression analysis model." (PMID 36733376, 2022). "Data shows that the raised levels of blood pressure and diabetes may be provoke for inflammatory cytokines IL-6, hs-CRP, and uric acid which are promising potential biomarkers for detecting CAD in individuals." (PMID 37323554, 2022). "Risk factors for failure of conservative management in humans include diabetes mellitus, a C-reactive protein (CRP) >115 mg/L, a leukocyte count >12 × 109/L, positive blood cultures, age >65 years, the presence of methicillin-resistant Staphylococcus aureus, and advanced neurological deficits." (PMID 35330611, 2022). "Moreover, several previous studies suggested that patients with high CRP levels have more severe conditions and comorbidities such as diabetes, atrial fibrillation and vascular disease." (PMID 35244369, 2022). "At univariate analysis, BNP, β2-MG, cFLCs, and sHMGB1 were significantly associated with the endpoint, whereas diabetes, ferritin, CRP, CD4+/CD8+ ratio, and age failed to reach statistical significance." (PMID 36498479, 2022). "This analysis shows that anemia is independently associated with increased risk for all fractures at 10 and 16 years after adjusting for age, year of birth, smoking, hip BMD, falls, stroke, cancer, diabetes, kidney function, testosterone and estrogen levels, CRP, and EPO." (PMID 35739404, 2022). "Also the prevalence of diabetes mellitus (P = 0.008) was higher in those with high hs-CRP compared to those with hs-CRP < 3, in high LDL-C group." (PMID 35614388, 2022). "Mortality increased among patients with the following characteristics: age, male gender, New York region, cardiac disease, COPD, diabetes mellitus, hypertension, history of cancer, immunosuppression, elevated lymphocytes, CRP, ferritin, D-Dimer, creatinine, troponin, and procalcitonin." (PMID 35715729, 2022). "In addition, the population with PC lesions was more likely to have diabetes, hyperlipidemia, and elevated high-sensitivity C-reactive protein (hi-CRP)." (PMID 35047049, 2022). "Experiments show that GMP can reduce the levels of IL-6, TNF- α, and CRP, increase the level of IL-10, and then alleviate the inflammatory reaction induced by diabetes and repair the phenomenon of hepatocyte lysis and inflammatory cell infiltration in mice, so as to improve the liver injury." (PMID 35399678, 2022). "Third, given the limitation of datasets, some diagnostic indicators involved in MAFLD were unavailable, including the HOMA-IR score, hs-CRP level, the specific type of diabetes, the duration of diabetes, drinking status, hepatitis B virus infection or other liver disease." (PMID 36374233, 2022).
diabetes (continued). "High levels of CRP indicate low-grade inflammation that is, often, associated with several non-communicable diseases, including obesity, cardiovascular disease (CVD), and diabetes." (PMID 36313082, 2022). "Only 5 strong predictors remained in the prediction model when the λ of LASSO regression was 0.0415, i.e., presence of diabetes mellitus and chills, neutrophil percentage > 75%, initial CRP level of 50–100 mg/L, and procalcitonin > 0.3 ng/mL within 24 h after admission." (PMID 36482449, 2022). "Individuals with abdominal obesity had higher frequencies of hypertension, osteoarthritis, diabetes, high C-reactive protein, low HDL cholesterol, and hypertriglyceridemia, and lower frequencies of high total cholesterol and LDL cholesterol than those without abdominal obesity (p < 0.05)." (PMID 36235815, 2022). "The variables that were associated with disease progression in a preliminary univariate analysis were included in the initial model, namely diabetes, obesity, significant lung involvement on admission, the CRP concentration, and all cell subsets with AUCs ≥ 0.65." (PMID 35806995, 2022). "The results of the subgroup analysis showed that the hs-CRP levels observed after stent implantation (≥6 months) were more effective in predicting the risk of ISR and were consistent after adjusting for two established ISR risk factors (age and diabetes)." (PMID 36005411, 2022). "After adjusting for age, gender, diabetes, Alb, Hb, Hs-CRP, and neutrophil/lymphocyte ratio, AID (adjusted HR = 1.85, 95% CI: 1.01–3.39, p = 0.04) and HIS (adjusted HR = 2.70, 95% CI: 1.39–5.25, p = 0.003) were found to be independent risk factors for treatment failure." (PMID 35458175, 2022). "Additionally, our regression analysis indicates that suPAR acts as a predictor for 30-day mortality both independently and when adjusted with age, NEWS scoring, CRP and comorbidities such as diabetes mellitus, cardiovascular diseases and neurological diseases." (PMID 35743359, 2022). "In a multivariable model adjusting for sex, age, body composition, pack-years, CRP, cholesterol/blood pressure lowering medication use and diabetes mellitus, the OR (95% CI) for having significant stenosis was 1.80 (0.86–3.78) in COPD patients compared with controls." (PMID 35476713, 2022). "Spearman correlation analysis showed that GRB2 concentrations were negatively correlated with HDL-C, and positively associated with duration of diabetes, waist-to-hip ratio (WHR), TC, HBA1c, FPG, FINS, homeostasis model assessment-insulin resistance index (HOMA-IR), Hs-CRP, IL-6 and CIMT (P<0.01)." (PMID 36176460, 2022). "On the other hand, the results derived from standard linear regression, from regression stratified by SB levels, from ISM and from compositional approaches are in disagreement for fasting glucose, 2-h glucose, 2-h insulin, insulin sensitivity, HOMA-IR, incident diabetes, CRP and IL-6." (PMID 35544519, 2022). "Inflammation is the main cause of developing type 2 diabetes mellitus, yet inflammatory markers are rather not specific (i.e. C-Reactive Protein or CRP) or not usually measured in clinic (i.e. interleukin 6 or IL-6)." (PMID 34991564, 2022). "In a person with diabetes and suspected osteomyelitis of the foot, we recommend using a combination of the probe-to-bone test, the erythrocyte sedimentation rate (or C-reactive protein and/or procalcitonin), and plain X-rays as the initial studies to diagnose osteomyelitis." (PMID 35676695, 2022). "The chosen studies were stratified according to the factors of study design, location, patient types, age, follow-up duration, and adjustment for race, body mass index (BMI), hypertension, diabetes, creatinine, C-reactive protein (CRP) as well as sex hormone binding globulin (SHBG)." (PMID 36124237, 2022).
diabetes (continued). "A 12-week intervention study documented that exercise could decrease the circulation of IL-6 in individuals with type 2 diabetes; 14-week aerobic exercise effectively reduced CRP by 15% among female patients with diabetes." (PMID 36590621, 2022). "The higher mortality rates of patients with both high CRP and high troponin could be explained by the higher prevalence of heart failure and diabetes among these individuals." (PMID 35566579, 2022). "Significantly, according to this model’s results, this effect was independent to CRP, arterial hypertension, diabetes mellitus, smoke status, body mass index, and sex, while increasing age could have concurred to the observed effect." (PMID 35407382, 2022). "Circulating levels of acute-phase proteins are elevated in diabetes, such as serum amyloid A, C-reactive protein (CRP), fibrinogen, haptoglobin, plasminogen activator inhibitor, sialic acid, interleukin (IL)-1β, IL-1 receptor antagonist (IL-1Ra), IL-6 and tumor necrosis factor (TNF)-α." (PMID 35327468, 2022). "A logistic regression model was created with all of the study variables (Cl, sex, age, cancer, renal failure, diabetes, septicemia, pO2, pH, pCO2, urea, Na, and CRP) that are thought to affect mortality in intensive care unit patients (p < 0.05, Hosmer and Lemeshow test)." (PMID 36422489, 2022). "Patients with diabetes and hypertension showed elevated IL-6, CRP, and CXCL-10 (p < 0.001)." (PMID 35967091, 2022). "Several studies show an association of the serum soluble RANKL (sRANKL) level with Body Mass Index (BMI), lipids profile, Homeostatic Model Assessment- Insulin Resistance (HOMA-IR), diabetes, blood pressure, C-reactive protein (CRP), carotid intima-media thickness (cIMT) and CV events." (PMID 36060948, 2022). "The well-known confounders include age, sex, NIHSS, LUBBEN, diabetes mellitus, CRP, and UA." (PMID 35309559, 2022). "However, the associations were no longer significant after adjustment for age, sex, ethnicity, education, smoking status, drinking, overweight/obesity, diabetes, hypercholesterolemia, antihypertensive medication use, eGFR, serum vitamin B12, and CRP." (PMID 35284465, 2022). "In conclusion, our study found a strong relationship between the risk of death and the presence of concomitant conditions such as hypertension, diabetes mellitus, cardiovascular diseases, lymphopenia, high CRP, raised D-dimer, and ferritin at the time of presentation." (PMID 36379528, 2022). "Patients in this cluster were found to have the highest overall cardiovascular risk profile including family history [HR = 1.530 (1.199–1.952), p = 0.001], high triglycerides, hs-CRP [HR = 1.015 (1.004–1.026), p < 0.01] as well as diabetes [HR = 1.390 (1.093–1.768), p < 0.01]." (PMID 35355960, 2022). "Furthermore, the TyG index was observed to be associated with the incidence of arterial stiffness assessed by baPWV after adjusting for age, sex, smoking, alcohol drinking, physical activity, MAP, diabetes, hs-CRP, and BMI at baseline." (PMID 34271940, 2021). "In addition, the patients’ BMI, eGFR, preexisting diabetes mellitus as well as circulating CRP levels were of prognostic relevance with respect to event-free survival." (PMID 34501358, 2021). "Meanwhile, patients with diabetes are more likely to have higher levels of inflammatory markers such as C-reactive protein, which may increase the burden of atherosclerosis." (PMID 34977188, 2021). "Partial correlation analyses showed that the plasma taurine level was positively related to the value of HOMA-β in both primiparas (r = 0.188, P = 0.004) and multiparas (r = 0.196, P = 0.015), with controlling for age, BMI, CRP, family history of diabetes, history of PCOS, and physical activity." (PMID 33846497, 2021). "Moreover, diabetes has been shown to accelerate the progression of AS by enhancing the inflammatory response measured by C-reactive protein, where an increase in the inflammatory response was observed within the aortic valve of AS patients." (PMID 35284496, 2021).
diabetes (continued). "Other clinical characteristics including gender, catheter ablation, hypertension, diabetes mellitus, high-sensitivity C reactive protein (hs-CRP), estimated glomerular filtration rate (eGFR), and body mass index (BMI) were comparable between the groups (p > 0.05)." (PMID 33934700, 2021). "Age, diabetes, renal and peripheral artery disease, carotid and coronary involvements, levels of hs-CRP and serum creatinine, miR-1-3p, miR-16-5p and miR-122-5p showed association with adverse cardiovascular events in the univariable Cox proportional hazard analysis." (PMID 34440258, 2021). "In multivariate analysis, only age (OR 1.033; 95% CI 1.011–1.055) and LDL-cholesterol level (OR 2.141; 95% CI 1.161–3.949) were associated with lesion complexity (> 1 complex anatomical feature) after adjustment for gender, diabetes, chronic statin therapy, FH diagnosis, and a CRP ≥ 3 mg/L." (PMID 33947397, 2021). "Clinical correlation of elevated high sensitivity CRP levels with the medical history of obesity, dyslipidemia, diabetes/hyperglycemia, hypertension, and hypercholesterolemia guides the prognostication of MACE and cardiovascular mortality across asymptomatic CVD patients." (PMID 34367842, 2021). "In the multivariate model, age, sex, uric acid, hypertension, diabetes mellitus, coronary artery disease, smoking, chronic obstructive pulmonary disease, creatinine, glucose, C‐reactive protein (CRP) and D‐dimer ≥ 500 ng/mL were taken into account, in addition to cardiac injury." (PMID 33860908, 2021). "Finally, a recent meta-analysis of vitamin D on the markers of inflammation and oxidative stress in people with diabetes found that vitamin D reduced C-reactive protein and malondialdehyde levels, both markers of inflammation." (PMID 34836301, 2021). "Despite these limitations, this study does provide insight into the association between fasting insulin and CRP in adults without diabetes." (PMID 33691751, 2021). "The significance of raised CRP and IL-6 in people with both depression and type 2 diabetes is unclear and may be important in the development of other diabetes-related complications." (PMID 33064180, 2021). "According to the univariate logistic regression analysis (crosstabs-relative risk), additional significant indicators included age, diabetes mellitus, heart failure, New York Heart Association (NYHA) III–IV, endocarditis vegetation size ≥10 mm, Staphylococcus aureus, troponin, CRP, and surgery." (PMID 34434979, 2021). "Indeed, Smad3 can be activated by both TGF-β-dependent and independent mechanisms including Ang II, advanced end products (AGE), and CRP under various disease conditions such as hypertension and diabetes 125-127." (PMID 33907513, 2021). "For example, in a study of 44 adults, aged ≥ 60 years, an interquartile increase in PM2.5 of the five-day mean was associated with a 14% (95%CI −5.4 to 37%) increase in CRP for all individuals and an 81% (95%CI 21 to 172%) increase in CRP among those with diabetes, obesity and hypertension." (PMID 33567509, 2021). "These variables included diabetes mellitus (OR 2.11; 95% CI 1.34–3.34, p = 0.001), SpO2:FiO2 Ratio (for every 100 increase, OR 0.42; 95% CI 0.34–0.53, p<0.001), CRP (log2-transformed value, OR 1.33; 95% CI 1.12–1.57, p = 0.001), and LDH (log2-transformed value, OR 2.08; 95% CI 1.34–3.23, p = 0.001)." (PMID 33655204, 2021). "The authors observed that in metabolic diseases, specifically in diabetes, the nonlinear associations of CRP with 25(OH)D had weakening tendency as 25(OH)D increased." (PMID 34033278, 2021). "Moreover, higher concentration of Cys was positively correlated with markers of inflammation including C-reactive protein (CRP) and tumor necrosis factor-α (TNF-α), suggesting higher risk of diabetes complications." (PMID 34335259, 2021).
diabetes (continued). "As previously reported in multiple studies, a high HGI was associated with black race independent of diabetes status, and with older age, higher BMI and higher CRP in normal and prediabetic but not diabetic participants." (PMID 34558807, 2021). "Patients with PAS had a significantly higher percentage of diabetes (p = 0.002), older age (p = 0.030), higher systolic blood pressure (p = 0.016), higher fasting glucose (p = 0.008), serum C-reactive protein (p = 0.002), and ANGPTL3 level (p = 0.001) than those without PAS." (PMID 34684048, 2021). "Furthermore, even fewer studies have been done on the relation between high sensitivity CRP and pre-diabetes." (PMID 34868746, 2021). "These associations were independent of age, sex, education, occupation, hypertension, diabetes, dyslipidaemia, smoking, alcohol consumption, physical activity, BMI, self-rated health, cancer, genitourinary disease, chest disease, platelet count and CRP." (PMID 34856939, 2021). "In terms of daily clinical practice, it was stated that increased IL6, IL1 β, and C-reactive protein (CRP) serum levels might precede the onset of type 2 diabetes mellitus, serving as accurate predictors for this condition." (PMID 34207683, 2021). "Moreover, with increasing FABP3 levels, the patients had higher rates of hypertension, diabetes mellitus, abnormal QTc interval, LVSD, and all-cause mortality, and higher levels of hs-CRP, WBC count, and visfatin." (PMID 33850478, 2021). "In multivariate regression based on clinical, biological and CT parameters, the extent of all opacities, and extent of consolidation were independent predictors of adverse outcomes, as were diabetes, heart disease, C-reactive protein, and neutrophils/lymphocytes ratio." (PMID 34069115, 2021). "Furthermore, APOE-ε4 dosage is strongly associated with lower levels of C-reactive protein (CRP), a lower incidence of diabetes and reduced regular use of aspirin." (PMID 34301914, 2021). "Therefore, the reduced levels of TNF- α and CRP in patients with type 2 diabetes mellitus complicated with moderate-to-severe chronic periodontitis are linked to the balance of blood glucose." (PMID 33832490, 2021). "The univariate logistic regression showed that potential factors influencing the presence of hepatic steatosis were a higher DICA score, total cholesterol, triglycerides, and CRP, as well as the presence of hypertension, diabetes mellitus type 2, and hypothyroidism." (PMID 35056346, 2021). "The following adjustments were performed in regression models: model 1, crude model; model 2: model 1 + age and sex; model 3, model 2 + BMI, serum albumin, and hemoglobin; model 4, model 3 + phosphorus, PTH, diabetes, hypertension, and cardiovascular disease; model 5, model 4 + eGFR and CRP." (PMID 34934591, 2021). "Furthermore, diabetes is accompanied by an inflammatory state and oxidative stress, which are characterized by elevated levels of C-reactive protein, tumor necrosis factor-alpha, interleukin-6, and reactive oxygen species." (PMID 34876114, 2021). "The second group of variables is termed Physiological Load, comprising clinical monitoring indicators associated with diabetes, such as body mass index (BMI), resting pulse rate (RPR), c-reactive protein (CRP), systolic (SBP), and diastolic (DBP) blood pressure." (PMID 34682644, 2021). "Participants with severe periodontitis presented higher BMI values (26.4 vs. 25.5 kg/m2), were current smokers (25.1 vs. 16.2%), had more often diabetes (11.3 vs. 6.2 %), suffered from hypertension (72.5 vs. 54.8%), and differed in their CRP values (0.10 vs. 0.13 mg/l)." (PMID 34836422, 2021). "To improve our interpretation of findings and produce more robust results, we adjusted for multiple potential confounding factors, including age, ethnicity, education, BMI, smoking status, alcohol, physical activity, energy intake, diabetes, hypertension, and C-reactive protein." (PMID 34603596, 2021).